MALINC1 (mitosis associated long intergenic non-coding RNA 1)
Synonyms: MA-linc1; formerly LINC01024
Gene: Long non-coding RNA gene on chromosome 5 (140,071,312 to 140,114,715, reverse strand). Ensembl gene ENSG00000245146.
Diseases named in the same sentence as MALINC1 in open-access papers:
MALINC1 is named in the same sentence as 7 diseases in open-access papers, as found by Europe PMC text mining. Sharing a sentence is not in itself a finding about the gene and the disease. The quoted sentences say what the papers report.
breast carcinoma (3 papers, 2022 to 2023). "We determined that MALINC1 is an estrogen–estrogen receptor-modulated lncRNA enriched in the cytoplasmic fraction of luminal A/B breast cancer cells that is associated with worse overall survival in patients with primary invasive breast carcinomas." (PMID 35740485, 2022). "Furthermore, the immune profiling described in our study suggests that high-MALINC1-overexpressing cells at pre-invasive and invasive stages are characterized by a tumor-associated immunosuppressive phenotype in luminal-like breast carcinomas." (PMID 35740485, 2022). "Here, we characterized for the first time the expression, molecular and phenotypic effects of MALINC1 in non-invasive and invasive breast cancer models." (PMID 35740485, 2022). "The aim of this study was to characterize MALINC1 expression, localization, and phenotypic and molecular effects in non-invasive and invasive breast cancer cells." (PMID 35740485, 2022). "We provide evidence that MALINC1 behaves as an oncogenic and immune-related lncRNA involved with early-stage breast cancer progression, showing prognostic and predictive value to immunotherapy in invasive breast carcinomas." (PMID 35740485, 2022). "Overall, our findings indicate that MALINC1 is a novel oncogenic and immune-related lncRNA involved in early-stage breast cancer progression." (PMID 35740485, 2022). "We conclude that MALINC1 behaves as an oncogenic and immune-related lncRNA involved with early-stage breast cancer progression." (PMID 35740485, 2022). "In addition, we determined that MALINC1 behaves as an E2-ER-modulated transcript predominantly found in the cytoplasmic compartment of luminal-like breast cells that may influence breast cancer progression, affecting patient outcome." (PMID 35740485, 2022). "MALINC1 was also shown to modulate JUN and FOS gene expression and AP-1 complex activity in the early stages of breast cancer and invasive breast carcinoma." (PMID 37240077, 2023). "In breast cancer, LINC01615, the long non-coding NKILA and MALINC1 have been reported to regulate breast cancer progression and metastasis." (PMID 36672487, 2023). "In an in silico analysis, the lncRNA MALINC1, upregulated in CDIS lesions, showed the presence of 4 ER binding sites (EREs) close to the transcription start site, indicating that, in breast cancer, its expression may be modulated by estrogen." (PMID 37240077, 2023).
breast ductal carcinoma in situ (1 paper, 2022). "The long non-coding MALINC1 intergenic RNA was identified as significantly upregulated in breast ductal carcinoma in situ." (PMID 35740485, 2022).
invasive carcinoma (1 paper, 2022). A carcinoma that is not confined to the epithelium, and has spread to the surrounding stroma. "Moreover, high MALINC1 expression in invasive carcinomas was associated with a pro-tumorigenic immune environment and a favorable predicted response to immunotherapy both in luminal and basal-like subtypes compared with low-MALINC1-expression tumors." (PMID 35740485, 2022). "More importantly, MALINC1 expression behaves as a predictive biomarker of immunotherapy response in luminal and basal-like primary invasive carcinomas that deserves further characterization." (PMID 35740485, 2022).
osteosarcoma (1 paper, 2022). A usually aggressive malignant bone-forming mesenchymal neoplasm, predominantly affecting adolescents and young adults. "In contemporaneous studies, LINC01024 was associated with cell-cycle progression of osteosarcoma cells and renamed MALINC1 (Mitosis-Associated Long Intergenic Non-Coding RNA 1)." (PMID 35740485, 2022).
tumor (2 papers, 2022 to 2023). "Thus, MALINC1 overexpression induced premalignant changes mainly associated with tumor microenvironment remodeling processes and the activation of several pro-tumorigenic signaling pathways, such as AP-1 and cell migration in normal breast, preinvasive, and invasive tumors." (PMID 37240077, 2023). "MALINC1 activation seems to help tumor progression with enhanced AP1 activity and a role in the microenvironment." (PMID 37240077, 2023). "Thus, experiments evaluating the functionality of these and other transcription factor-binding sites on the MALINC1 promoter are required to understand its regulation and the time points in tumor progression from DCIS to IBC in which it plays a role." (PMID 37240077, 2023). "Therefore, BHLHE40-AS1 could help MALINC1 turn the tumor microenvironment into a permissive space for tumor progression." (PMID 37240077, 2023).
MALINC1 also shares sentences with these, for which no sentence is quoted: cancer (1 paper); invasive breast carcinoma (1).